MMP2 (matrix metallopeptidase 2)
Diseases named in the same sentence as MMP2 in open-access papers (continued):
Sharing a sentence is not in itself a finding about the gene and the disease.
ovarian tumor (18 papers, 2011 to 2024). "On the other hand, MMP-2 in the epithelial cells of the ovarian tumor predicts an increased risk of death." (PMID 32718331, 2020). "Previous data from our group in prostate and ovarian tumor models showed that cells overexpressing the OPNc variant induce expression of MMP2 and MMP9, highlighting the functional tissue specificity of OPN-SV." (PMID 27409830, 2016). "Overproduction and unrestrained activity of MMP2 has been linked to malignancy in a variety of tumors, including brain, prostate, colorectal, pancreatic, breast, and ovarian tumors, and has been associated with shorter disease-free survival." (PMID 26540114, 2015). "The expression of MMP-2 and MMP-9 showed a significant association with the presence of androgen receptor in the epithelium of the total ovarian tumors." (PMID 32718331, 2020). "Kaplan-Meier analysis shows that the overall survival time of the patients with ovarian tumors is increased by the presence of MMP-2 in the stroma, which has a protective effect indeed." (PMID 32718331, 2020). "Although further information will be required in order to explain the relationship between AR and MMP-2 in ovarian tumors." (PMID 32718331, 2020). "The presence of MMP-2 in the epithelium and stroma of the tumor has a particular distribution in the subtypes of ovarian tumors; in the case of LGSC and the borderline serous tumor the presence of MMP-2 in stroma is similar to the epithelium." (PMID 32718331, 2020). "MMP-2 and MMP-9 were differentially expressed in the epithelium and the stroma of ovarian tumors associated to histological subtype, clinical stage and sexual steroid hormone receptor expression." (PMID 32718331, 2020). "Subsequently Autio-Harnainen found expression of MMP-2 in both epithelial and stromal cells by immunohistochemistry in their studies of ovarian tumors." (PMID 24245968, 2013). "Most of the ovarian tumor cells expressed MMP-2 and MMP-9 (pro-forms) weakly as previously observed; however, the tumor cells with partial EMT phenotypes had higher levels." (PMID 21526198, 2011). "The meta-analysis data has shown that MMP2 overexpression in ovarian tumor cells contributes to shortened overall survival, but upregulation of stromal MMP2 might be protective." (PMID 38397798, 2024). "Besides, it was described that fibroblasts stimulated with ovarian tumor-EV had a higher secretion of the inactive form of MMP2." (PMID 37569393, 2023). "Interestingly, the frequency of MMP-2 presence is significantly reduced in the stroma of ovarian tumors classified as FIGO stages III and IV." (PMID 32718331, 2020). "The current study evaluated the metalloproteinases MMP-2 and MMP-9 expression in epithelial cells and the surrounding stroma in ovarian tumors and the association of MMPs with the histological subtypes, the clinical stage and the presence of steroid hormone receptors." (PMID 32718331, 2020). "Additionally, we showed activity of the Prot-FOLR1-TCB containing MMP-2, -9-matriptase cleavable linker in undigested human ovarian tumor samples." (PMID 32581215, 2020). "It was demonstrated that VEGF increased the release of MMP2 in brain and ovarian tumor cells." (PMID 23226772, 2012). "This research was conducted to examine the expression of claudin-6, occludin and MMP-2 in 36 ovarian papillary serous carcinomas and 26 ovarian serous adenomas specimens, and investigate the relationship between their expression and clinical properties of the ovarian tumor patients." (PMID 24245968, 2013). "This suggests that in the context of behavioral disorders or low social support, elevated levels of stress hormones can lead to upregulation of MMP-9, MMP-2, and VEGF expression in ovarian tumor cells via β-adrenergic receptor signaling." (PMID 38254696, 2024). "The aim of the current study was to evaluate the frequency of MMP-2 and MMP-9 expression in epithelial tumor cells and the surrounding stroma in ovarian tumors." (PMID 32718331, 2020).
ovarian tumor (continued). "While both fallopian tube tumor- and ovarian tumor-derived mouse model cell lines expressed epithelial cytokeratins, they expressed only E-cadherin cleaved fragments and the EMT marker MMP2." (PMID 27602775, 2016). "The analysis of this cohort provides evidence of the presence of MMP-2 and MMP-9 in the epithelium and stroma of ovarian tumors, showing variations in the presence of MMPs when stratified by histological subtypes, FIGO stages and expression of AR, ERα, and PR in the ovarian tumor as well." (PMID 32718331, 2020). "Moreover, several invasion-related proteins such as MMP2, MMP9, and N-Cadherin have positive correlation with BCL6 in ovarian tumor cells." (PMID 30420967, 2018). "By univariate analysis, high levels of MMP-2, MMP-9, MT1-MMP and TIMP-2, were detected by immunohistochemistry and/or mRNA in situ hybridization in tumor cells from peritoneal or pleural effusions, metastatic lesions and primary ovarian tumors." (PMID 22200690, 2012).
prostate tumor (18 papers, 2005 to 2025). "It has been also demonstrated that prostate tumor cells with increased levels of SRD5A2 expression exhibit significantly reduced matrix metallopeptidase 2 (MMT2) activity compared to control cells." (PMID 37784175, 2023). "High expression and secretion of MMP-2 and MMP-9 have been associated with increased prostatic tumor invasion, an important phenomenon for subsequent tumor metastasis." (PMID 38137922, 2023). "MiR-29b is expressed at low levels in prostatic tumor tissues and, when upregulated, inhibits Mcl-1, matrix metalloproteinase-2 (MMP-2), and collagen." (PMID 35898539, 2022). "Another study showed that IL-10 stimulated TIMP-1 secretion and inhibition of MMP-2, 9 by prostate tumor cells." (PMID 33841538, 2020). "Prostate tumours, in particular, express increasing amounts of MMP2 and MMP9 as they progress to higher-grade tumours and greater degrees of metastatic potential." (PMID 18182993, 2008). "Moreover, the prostate tumours had high levels of gelatinase (MMP2 and MMP9) expression and activity." (PMID 18182993, 2008). "Melatonin can inhibit SIRT1 to modulate MMP2 activity, which was shown to impact the degradation of the ECM and exert anti-proliferative effects on prostate tumor cells." (PMID 39796199, 2025). "MT-MMP1 activation in the extracellular space allows cleavage of the inactive pro-MMP-2 protein to active MMP-2, resulting in increased extracellular matrix degradation and augmented pCAF invasion into the prostate tumour." (PMID 38958472, 2024). "Distinctly, IL-10 has been shown to stimulate TIMP-1 secretion and inhibit the secretion of MMP-2 and MMP-9 by prostate tumor cells." (PMID 33841538, 2020). "The present results highlight the potential value of MMP-2 and MMP-9 expression for predicting the behavior of prostate tumors after prostatectomy with both positive and negative surgical margins." (PMID 25097794, 2014).
metastatic carcinoma (17 papers, 2005 to 2024). A carcinoma which has spread from the original site of growth to another anatomic site. "Matrix metalloproteinase 2 (MMP-2) in metastatic cancer tissue, which is associated with a poor prognosis, is a potential target for tumor imaging in vivo." (PMID 25547485, 2014). "In spite of Cl channels, MeICT also interact to MMP-2 that is overexpressed in various metastatic cancers." (PMID 37201031, 2023). "Previous studies presented a close relationship between the upregulation of MMP-2 and the metastatic cancers, and the elevated MMP-2 usually predicted a worse prognosis and more aggressive tumor behavior." (PMID 33817311, 2021). "Regarding the role of the MDEs in our model, we found that both less MMP-2 production as well as less MMP-2 diffusion caused faster cancer cell invasion and thus a higher metastatic cancer cell load after 22 days." (PMID 30903592, 2019). "Previous studies have shown that the upregulation of MMP-2 is closely related to metastatic cancers." (PMID 29466303, 2018). "Immunohistochemical studies have indicated that MMP-2 is highly expressed in more invasive and metastatic cancer tissues." (PMID 16168111, 2005). "For instance, nuclear MT1-MMP or nuclear/nucleolar MMP-2 may be defined as novel therapeutic targets for metastatic cancer." (PMID 36076910, 2022). "Moreover, S1P and IgE/Ag we show can stimulate the secretion of MMP-2 from human primary MC possibly extending their contribution as connectors of inflammation to metastatic cancer." (PMID 26884643, 2016). "MMP-2 was found to promote ECM degradation and metastatic niche formation, which stimulates metastatic cancer cell growth." (PMID 37373007, 2023). "The increased expression of matrix metalloproteinase 2 (MMP2) and MMP9, regulated by MAPK and often found in metastatic cancers, could so be suppressed by ISA." (PMID 39376605, 2024). "MMP-2 and MMP-9 are the predominant enzymes found overexpressed in metastatic cancers." (PMID 37516013, 2023). "In particular, MMP-2 and MMP-9 were found to be up-regulated in metastatic cancer cell lines." (PMID 28465354, 2017). "This may be due to the expression of hyaluronidases and matrix metalloproteinases, such as MMP-2 and MMP-9, among advanced and metastatic cancers that cleave ECM (including hyaluronic acid) and reduce cell-ECM contacts, adhesion, and the associated intracellular signaling." (PMID 33019572, 2020).
multiple sclerosis (17 papers, 2013 to 2024). A progressive autoimmune disorder affecting the central nervous system resulting in demyelination. "The aim of this study was to determine the relationship between the MMP-2 (-1306 C/T)rs243865 gene polymorphism and ON, and that of ON with multiple sclerosis." (PMID 30344260, 2018). "For example, increased levels of MMP-2 and -9 have been associated with BBB failure in multiple sclerosis, while MMP-3 and -13 were increased in the brains of subjects with HAND." (PMID 37496706, 2023). "MMPs are effectors of BBB disruption, and extensive studies in multiple sclerosis and experimental autoimmune encephalomyelitis have highlighted the activities of MMP-2 and MMP-9 in BBB disruption." (PMID 26934979, 2016). "Several experimental evidence indicate the involvement of gelatinases A (MMP-2) and B (MMP-9) in the pathogenesis of HIV-associated dementia (HAD), Multiple Sclerosis (MS) and cancer progression." (PMID 26053757, 2015). "There are reports that MMP-2 phosphorylation modulates its proteolytic activity in the human fibrosarcoma cell line and detection of heterogeneous isoforms of gelatinases in sera of multiple sclerosis patients." (PMID 25859655, 2015). "The remaining genes included MMP2, a modulator of neuronal precursor activity and cognitive and motor behaviors; CFB, a complement factor altered in neurologic diseases such as multiple sclerosis; and HOXB3, a critical choreographer of neural development." (PMID 38376950, 2024). "The matrix metalloproteinases (MMPs) gelatinase A (MMP-2) and gelatinase B (MMP-9) are mediators of brain injury in multiple sclerosis (MS) and valuable biomarkers of disease activity." (PMID 24616914, 2014). "In any case, reactive astrocytes and activated microglia both produce MMP-2 and MMP-9 in a number of CNS disorders, including AD and multiple sclerosis." (PMID 24188129, 2013).
astrocytoma (16 papers, 2000 to 2025). "High MMP-2 expression was significantly associated with poorer survival in patients with grade II-IV astrocytoma when dichotomized at the median intensity of 117.1 (HR 1.60; 95% CI 1.03–2.48; p = 0.036)." (PMID 28234925, 2017). "The MMP-2 level increased with malignancy grade, and high expression was associated with shorter survival in patients diagnosed with grade II-IV astrocytomas as well as in patients with GBM who lived longer than 8.5 months after initial diagnosis." (PMID 28234925, 2017). "In survival analysis, high MMP-2 expression was associated with poorer outcome in patients with grade II-IV astrocytomas (HR 2.54; 95% CI 1.86–3.48; p<0.001)." (PMID 28234925, 2017). "In line with previous results, we confirmed that MMP-2 is expressed in astrocytomas with the highest level in GBMs and found that high levels of MMP-2 were inversely related to survival in patients with grade II-IV astrocytic tumors." (PMID 28234925, 2017). "MMP-2 expression was found to significantly increase with malignancy grade, and high levels correlated with poor prognosis in patients with grade II-IV astrocytomas." (PMID 28234925, 2017). "The aim of this study was to investigate the expression and prognostic potential of MMP-2 in astrocytomas." (PMID 28234925, 2017). "In astrocytomas, MMP-2 was mainly expressed in the cytoplasm, but was also present in the membranes and ECM." (PMID 28234925, 2017). "Investigating the association between IDH1 status and MMP-2 levels in grade II-III astrocytomas, patients with wildtype IDH1 tumors (wtIDH1, n = 10; mean: 106.0 ±4.0) tended to have higher MMP-2 intensity than patients with mutated IDH1 tumors (mIDH1, n = 7; mean: 97.9 ±3.2) (p = 0.17)." (PMID 28234925, 2017). "However, TNF-α has been reported to down-regulate expression and secretion of MMP-2 from both astrocytoma and choroid plexus epithelial cells." (PMID 21569377, 2011). "However, in microglial cells decreased MMP-2 secretion was mainly due to inhibition of MMP-2 mRNA accumulation, a phenomenon only previously reported in astrocytoma cells." (PMID 21569377, 2011). "A strong correlation between elevated expression levels of MMP-2, MMP-9, as well as membrane-associated MMPs, with higher grade astrocytomas has been described, suggesting that inhibitors of these MMPs may modulate astrocytoma progression." (PMID 26431549, 2015). "The last examined protein, OPN, is also better investigated as a potential astrocytoma marker than AREG and MMP-2." (PMID 33227903, 2020). "To further investigate the influence of MMP-2 and TIMP-1 on tumor aggressiveness and prognosis in patients with astrocytomas, we evaluated mRNA expression levels in TCGA." (PMID 28234925, 2017). "We examined the mRNA expression profiles of RECK transcripts, as well as of MMPs reportedly inhibited by canonical RECK (MMP-2, -9 and -14), and of endogenous tissue inhibitors of MMPs (TIMP-1, TIMP-2, TIMP-3 and TIMP-4) in astrocytomas of different grades of malignancy." (PMID 26431549, 2015). "High expression of MMP-2, -9 and -14 was found in astrocytomas, when compared to the non-tumoral control group." (PMID 26431549, 2015). "Recent proteinase profiling studies have demonstrated the over-expression of the serine urokinase-type plasminogen activator (uPA) and its receptor (uPAR), cysteine protease cathepsin B, MMP-2, and MMP-9 in high grade astrocytomas compared with low grade astrocytomas or the normal brain." (PMID 20587068, 2010). "The MMP-2 and GFAP proteins did not demonstrate any statistically significant expression differences between different malignancy grades and different IDH1 mutational status astrocytoma groups, or between the astrocytoma and healthy control groups." (PMID 33227903, 2020).
injury (16 papers, 2012 to 2024). Damage inflicted on the body as the direct or indirect result of an external force, with or without disruption of structural continuity. "In traumatic brain injury, inhibition of Adam10 attenuated the upregulation of Mmp2 and Mmp9 expression." (PMID 35163191, 2022). "Past studies have also linked induction of MMP2 and MMP9, and degradation of the ECM, to immune-mediated acute lung injury, and local MMP2 upregulation has been observed in experimental cerebral malaria." (PMID 33563839, 2021). "In light of these findings, we conclude that extracellular UTP (which mimics nerve injury) stimulates Schwannoma cell migration and wound repair through a MMP-2-dependent mechanism via P2Y2 receptors and the activation of MAPK pathways." (PMID 24905332, 2014). "This review discusses the intracellular mechanisms controlling MMP-2 activity and highlights a new intracellular therapeutic direction for the prevention and treatment of heart injury." (PMID 24455428, 2013). "MMP-2 and/or MMP-9 have also been implicated in the development of experimental acute lung injury." (PMID 30616599, 2019). "Male Nrf2 knock-out (Nrf2−/−) control mice had significantly higher HNE and NT levels, moreover in these mice the level of MMP-2 and MMP-9 significantly increased in cortical brain tissue lysate compared to wild-type (WT or Nrf2+/+) control animals in traumatic brain injury animal model." (PMID 33076449, 2020). "MMP-2 and MMP-9 are produced mainly by the microglia in a rat traumatic brain injury model." (PMID 25925889, 2015). "Our previous study showed that intrathecal injections of MMP-9 siRNA specifically reduced MMP-9 but not MMP-2 activity in DRGs after nerve injury." (PMID 22444868, 2012). "Moreover, MMP-2 contributes to acute cardiac dysfunction through the degradation of intracellular contractile machinery proteins, such as troponin I (TnI), titin, myosin light chains 1 and 2 (MLC1 and 2) in oxidative-stress-induced-heart injury." (PMID 38540247, 2024).